RYR2 (ryanodine receptor 2)
Diseases named in the same sentence as RYR2 in open-access papers (continued):
Sharing a sentence is not in itself a finding about the gene and the disease.
diabetes (continued). "Chronic hyperglycaemia and insulin resistance in diabetes impair calcium cycling in cardiomyocytes by reducing SERCA2a activity, increasing RyR2 leakiness, and promoting mitochondrial calcium overload, ultimately leading to diastolic dysfunction and myocardial fibrosis." (PMID 40771931, 2025). "Unlike mutations in monogenic diabetes genes, pathogenic missense variants in RyR2 result in normal fasting glucose levels with impaired glucose tolerance at an early age." (PMID 38444585, 2024). "In conclusion, we have identified an atypical missense variant in the RyR2 gene that co-segregates with diabetes in the absence of overt CPVT." (PMID 38444585, 2024). "Is the RyR2 GOF causing glucose intolerance and promoting diabetes?" (PMID 34725342, 2021). "The hyper-phosphorylation of RyR2 is shown in heart of diabetes." (PMID 34639137, 2021). "Early studies of RyR2-mediated Ca2+ release in diabetes utilized STZ-diabetic rat models." (PMID 30425651, 2018). "Dysregulation of the type 2 ryanodine receptor (RyR2) has been detected in a STZ-induced diabetes rat model, in which increased frequency of Ca2+ sparks with reduced amplitudes was associated with increased sensitivity to Ca2+ activation and dyssynchronous Ca2+ release." (PMID 27642609, 2016). "Shortly, diabetes is accompanied by increased oxidative stress and defective antioxidant defence system via increased ROS/RNS production, which can cause changes in RyR2 function as well as release of Zn2+ from intracellular stores." (PMID 24693334, 2014). "We thus for the first time report that an enhancement of antioxidant defence in diabetics via directly targeting heart seems to prevent diastolic dysfunction due to modulation of RyR2 macromolecular-complex thereby leading to normalized [Ca2+]i and [Zn2+]iin cardiomyocytes." (PMID 24693334, 2014). "Under most pathological conditions including diabetes, alterations in the characteristics of intracellular basal free Ca2+ transients occur in combination with altered phosphorylated levels of RyR2 (pRyR2; 565 kDa phospho-RyR2-Ser2808)." (PMID 23923043, 2013). "This increased concentration of ROS and RCS may result in the phosphorylation of RyR2 in diabetes." (PMID 38961333, 2024). "Indeed, the increased O-GlcNAcylation of CaMKII and subsequent phosphorylation of RyR2 is already established to drive arrhythmias in diabetes, suggesting that prevention of CaMKII O-GlcNAcylation may be a therapeutic strategy." (PMID 37833717, 2023). "Thus, the key to understanding the link between RCS and changed RyR2 in the cardiac origin and lungs in patients with diabetes could assist with the management of diabetes complications." (PMID 35268685, 2022). "Alteration in the sensitivity of RyR2 to the Ca2+ activation, oxidation of RyR2 by ROS and/or reactive carbonyl species, and functional uncoupling of RyR2 from L-type Ca2+ channels on the T-tubule membranes could be partly responsible for the dyssynchronous Ca2+ release from SR in diabetes." (PMID 33274235, 2020). "Therefore, GCH1 overexpression may exert favorable effect on RyR2-mediated Ca2+ release via nNOS in diabetes." (PMID 27295516, 2016). "Studies using RyR2-S2814D knock-in mice, which mimic constitutive phosphorylation of RyR2, show that chronic gain-of-function in RyR2 leads to basal hyperglycemia, impaired GSIS, and glucose intolerance—hallmarks of pre-diabetes and early T2DM." (PMID 40422193, 2025). "Islets obtained from human diabetes subjects show increased oxidation, increased nitrosylation of RyR2, and decreased binding of FKBP12.6 to RyR2." (PMID 40422193, 2025). "Other key ion channels found to be downregulated in diabetes include sarco-endoplasmic reticulum calcium ATPase (SERCA) and Ryanodine Receptor 2 (RYR2), which are responsible for sarcoplasmic Ca2+ uptake and release, respectively." (PMID 37719978, 2023). "In diabetes, RCS changes RyR2 proteins, resulting in RyR2 dysfunction in both the heart and the lungs." (PMID 35268685, 2022).
diabetes (continued). "Instead, this phenomenon was attributed to significantly increased RyR2 oxidation in HFD-mice, implicating the diabetes-related increase in oxidative stress in abnormal Ca2+ handling." (PMID 30425651, 2018). "We also showed that levels of the major Ca2+ channel proteins, RyR2, SERCA, and NCX1 declined in a time-dependent manner with the progression of diabetes." (PMID 24712865, 2014). "Although we did not see a change in O-GlcNAcylation of RyR2 in diabetes, we were able to manipulate O-GlcNAcylation levels of RyR2 in HEK 293 cells." (PMID 37833717, 2023). "We also found that GCH1 overexpression increased the expression of RyR2 and SERCA2a proteins in nondiabetics and prevented diabetes-induced decreases in these two SR Ca2+ handling proteins." (PMID 27295516, 2016). "In the present study, GCH1 overexpression restored decreased RyR2-mediated Ca2+ release by diabetes, and the beneficial effects of GCH-1 overexpression on RyR2-mediated Ca2+ release were abrogated by S-methyl-L-thiocitrulline (SMTC, a specific inhibitor of nNOS)." (PMID 27295516, 2016). "Abnormal RyR2 gating mechanism may arise from increased phosphorylation by protein kinase A (PKA, serine 2808) and Ca2+/calmodulin-dependent protein kinase II (CaMKII, serine 2808 and serine 2814), as well as oxidation by ROS and reactive carbonyl species (RCS), which are increased in diabetes." (PMID 27642609, 2016).
Arrhythmogenic right ventricular dysplasia (25 papers, 2007 to 2026). "The known diseases caused by mutations in the RYR2 gene are catecholamine-sensitive polymorphic ventricular tachycardia and arrhythmogenic right ventricular cardiomyopathy." (PMID 37907926, 2023). "There are mutations in RYR2 gene that have been associated with stress-induced polymorphic ventricular tachycardia and arrhythmogenic right ventricular dysplasia." (PMID 36233078, 2022). "Mutations in the cardiac ryanodine receptor (RYR2) gene have been reported to cause arrhythmogenic right ventricular cardiomyopathy." (PMID 35048506, 2022). "Stress induced polymorphic ventricular tachycardia (PVT) and arrhythmogenic right ventricular dysplasia are conditions associated with RyR2 defects." (PMID 30400228, 2018). "Human RYR2 mutations are associated with stress-induced polymorphic ventricular tachycardia and arrhythmogenic right ventricular dysplasia." (PMID 27604219, 2016). "The RYR2 gene mutations are also a cause of arrhythmogenic right ventricular cardiomyopathy (ARVC2) with clinical manifestations similar to CPVT, such as stress‐induced ventricular tachycardia, in addition to ongoing deterioration and fibro–fatty infiltration of the right ventricle." (PMID 41510139, 2026). "Other diseases that are caused by mutations to the RyR2 channel include arrhythmogenic right ventricular dysplasia, type 2 (ARVC/D2), polymorphic ventricular tachycardia (PVT), sudden infant death syndrome (SIDS), sudden cardiac death (SCD), and left ventricular non-compaction (LVNC)." (PMID 32899693, 2020). "Mutations in this gene are associated with stress-induced polymorphic ventricular tachycardia and arrhythmogenic right ventricular dysplasia and methylation analysis of CpG sites in DNA from blood cells showed a positive correlation between RYR2 and age." (PMID 31706268, 2019). "Two common single nucleotide polymorphisms in exon 37 of the human RYR2 gene, causing non-conservative amino acid exchanges, i.e., G1885E and G1886S, have been associated with arrhythmogenic right ventricular cardiomyopathy (ARVC)." (PMID 31426283, 2019). "Ryanodine receptor 2 (RYR2) is found in cardiac muscle as part of a calcium channel and mutations in RYR2 gene may be associated with Alzheimer’s, tachycardia, arrhythmogenic right ventricular dysplasia." (PMID 24476026, 2014). "Single-point mutations in RyR2 have been reported to induce arrhythmogenic disorders including catecholaminergic PMVT (CPVT) and arrhythmogenic right ventricular dysplasia (ARVC/D2) under stress conditions." (PMID 37740238, 2023).
dilated cardiomyopathy (22 papers, 2010 to 2025). "Furthermore, mutations of RYR2, which is responsible for SR Ca2+ release, are associated with various CVDs, including dilated cardiomyopathy and hypertrophic cardiomyopathy." (PMID 34912794, 2021). "Rare diseases (monogenic), such as hypertrophic cardiomyopathy (e.g., MYBPC3, MYH7 mutations), dilated cardiomyopathy (LMNA, RBM20), or inherited arrhythmias (KCNQ1, RYR2), are often caused by single, well-characterized mutations." (PMID 40465697, 2025). "Upregulation of RyR2 can alter channel stoichiometry with detrimental consequences for cardiomyocytes function and increased Ca2+ sensitivity of cardiac myofilaments, such as in the dilated cardiomyopathy secondary to anthracyclines treatment." (PMID 29554110, 2018). "For example, decreased MYL2 and MYH6 gene expression coincided with increased RYR2, HCN4, CORIN, NPPA, ERBB2, and MYH7 gene expression in hypertrophic and/or dilated cardiomyopathy." (PMID 32804947, 2020). "We observe enrichment of cardiac disease pathways such as “Viral myocarditis,” “Hypertrophic cardiomyopathy,” and “Dilated cardiomyopathy,” mainly through the inclusion of ITGB and TGFB gene family members and RYR2." (PMID 30405693, 2018). "Chronic heart failure is associated with anincrease in circulating catecholamines, PKA phosphorylation of RyR2 ismarkedly increased in failing human hearts, and mice with constitutiveactivation of PKA show hyperphosphorylation of RyR2 and dilated cardiomyopathy." (PMID 20448293, 2010).
cardiac hypertrophy (21 papers, 2014 to 2026). "The RYR2 gene was linked to 60 different cardiovascular diseases, the majority of which affect the functionality of ventricular hypertrophy." (PMID 35629146, 2022). "The RYR2 gene was linked to 60 different cardiovascular disorders, the majority of which affect the functionality of ventricular hypertrophy." (PMID 35629146, 2022). "Phenomenologically, these results are consistent with a previously reported loss of mito-Ca2+ in disease models with enhanced RyR2 activity, i.e., guinea pig HF and rat model of cardiac hypertrophy induced by pressure overload." (PMID 32444920, 2020). "In the very initial phase of pressure-overload induced cardiac hypertrophy, when cardiac contractile function is preserved, reactive oxygen species (ROS)-mediated RyR2 destabilization already occurs in association with relaxation dysfunction." (PMID 33244105, 2020). "Increased SR Ca2+ leak during diastole as a result of RyR2 dysfunction is a hallmark of cardiac hypertrophy and HF and serves as a major mechanism of rhythm disturbance in these conditions." (PMID 25014109, 2014). "Substitution of three amino acid residues in the CaM binding domain of RyR2 (RyR2-W3587A/L3591D/F3603A, RyR2ADA) impairs inhibition of RyR2 by CaM and results in cardiac hypertrophy and early death of mice carrying the RyR2ADA mutation." (PMID 25093823, 2014). "Notably, the better preserved Serca2a and RyR2 expression in Miat-KO mice precedes the alleviation of cardiac hypertrophy, suggesting a causal role of Miat-mediated Serca2a and RyR2 downregulation in the pathogenesis of cardiac hypertrophy." (PMID 34335976, 2021). "Similarly, knockout of RyR2 is embryonic lethal with abnormal cardiomyocytes 48, and mutation of Ryr2 results in early cardiac hypertrophy and lethality." (PMID 34335976, 2021). "Taken together, it is strongly suggested that the defective interaction of CaM with RyR2 is a key factor in driving cardiac hypertrophy via the two major hypertrophic signaling pathways." (PMID 36926278, 2023). "Our results showed that genetic rescue of CaM dissociation from RyR2 prevents Ca2+ leakage, thereby protecting against cardiac hypertrophy and improving prognosis." (PMID 33244105, 2020). "VEGFs have been previously shown to induce a gene expression programme consistent with compensatory cardiac hypertrophy, by elevation of Anf, Bnp, αMHC, Serca-2α, Ryr2 and Pgc1α, and by inhibition of βMHC and skeletal alpha-actin (sk α-act)." (PMID 26092119, 2015). "CaMKII phosphorylated RyR2 to a similar extent in wild-type and mutant hearts in late stage severe cardiac hypertrophy." (PMID 25093823, 2014). "RyR2 knockdown suppresses CaN activation and pressure overload-induced cardiac hypertrophy." (PMID 40551210, 2025). "Additionally, the association of nesprin-1α2 and AKAP6 was shown to be necessary for the NE localisation of RyR and AKAP6-mediated cardiac hypertrophy in rat hearts occurred via RyR2 phosphorylation." (PMID 37171063, 2023). "Our study uncovers a critical missing link between RyR2 destabilization and cardiac hypertrophy." (PMID 33244105, 2020). "Ryr2ADA/ADA mice have three substituted amino acid residues in the calmodulin (CaM) binding domain of RyR2 (RyR2-W3587A/L3591D/F3603A, RyR2ADA) that disrupt its CaM inhibition at diastolic and systolic Ca2+ concentrations and result in cardiac hypertrophy and the early death of RyR2ADA/ADA mice." (PMID 25093823, 2014). "Enhanced RyR2 function activates the CaN/ Nuclear factor of activated T-cells (NFAT) and CaN/Myocyte enhancer factor 2 (MEF2) pathways, leading to cardiac hypertrophy." (PMID 40551210, 2025). "In conclusion, the results suggest that CaMKII does not have an essential role in the rapid development of cardiac hypertrophy and early death of mutant mice impaired in CaM regulation of RyR2 at diastolic and systolic Ca2+ concentrations." (PMID 25093823, 2014).
cardiac hypertrophy (continued). "The present study shows that CaMKII inhibitory peptide AC3-I reduced phosphorylation of PLN at Thr-17 in Ryr2+/+ and Ryr2ADA/ADA mice without significantly altering life span, cardiac morphology and performance, or markers of cardiac hypertrophy relative to mice expressing the control peptide." (PMID 25093823, 2014).
myocardial infarction (21 papers, 2013 to 2025). Gross necrosis of the myocardium, as a result of interruption of the blood supply to the area, as in coronary thrombosis. "It has been shown that redox-dependent PTMs of RyR2 contribute to abnormal Ca2+ regulation during myocardial infarction and heart failure." (PMID 37495581, 2023). "DHI and TMZ increased cardiac myocyte contractile function after myocardial infarction by enhancing SR calcium loading and RyR2 activity to increase sensitivity to calcium release." (PMID 33510801, 2021). "Jph2 gene therapy in mice with HF was shown to normalize RyR2-induced calcium release, while β-adrenergic receptor blocker treatment improved TT integrity and Jph2 expression in mice after myocardial infarction." (PMID 31810440, 2019). "Following myocardial infarction, the cross-bred mice had less mitochondrial Ca accumulation than their RyR2-S2808D counterparts and their progression towards HF was markedly slowed." (PMID 27508064, 2016). "TRPML1 agonist ML-SA1 could increase Ca2+ spark frequency in myocardial infarction (MI) CMs, which could be eliminated by SR RyR2 inhibition." (PMID 37303713, 2023). "RyR2 activity was reduced after myocardial infarction and upregulated after DHI and TMZ treatment." (PMID 33510801, 2021). "We tested whether exercise training (ET), as recommended by current guidelines, had the potential to stabilize RyR2-dependent Ca2+ release in rats with post-myocardial infarction HF." (PMID 33569394, 2020). "Interestingly, high-resolution imaging of cMyBP-C and RyR2 revealed that sarcomere-bound cMyBP-C is the predominant form in healthy cardiomyocytes, with significant release of cMyBP-C into the cytosol after myocardial infarction/reperfusion and in pathologic hypertrophy." (PMID 29930088, 2018). "The overexpression of cardiac FKBP12.6 in the mouse model has shown to reduce the probability of RyR2 opening, but this method is not sufficient to prevent and mitigate remodeling after myocardial infarction." (PMID 32581817, 2020). "WXKL treatment significantly reduced the expression of CaMKII, p-CaMKII (Thr-286), and PLB but significantly increased the expression of RYR2, p-PLB (Thr-17), and FKBP12.6 in rats with myocardial infarction to improve cardiac function and inhibit myocardial remodelling." (PMID 23781262, 2013). "Treatment with WXKL or amiodarone significantly increased the expression of RyR2 and FKBP12.6 in rats with myocardial infarction, which may enhance the ability of FKBP12.6 to modulate the RyR2 ion channel." (PMID 23781262, 2013). "Meanwhile, studies showed that SMY can inhibit calcium overload and the increase in oxygen free radicals in myocardial cells after myocardial infarction, the mechanism of which may be that SMY can up-regulate the expression of SERCA2 and RyR2 mRNA in myocardial cells." (PMID 32436944, 2020). "Similarly to CaMKII Knock out mice, RyR2-S2814A knock-in mice were protected against abnormal SR Ca2+ leak and HF after transverse aortic constriction (TAC) but surprisingly not after myocardial infarction (MI)." (PMID 34690808, 2021).